CCNG1 (cyclin G1)
Diseases named in the same sentence as CCNG1 in open-access papers (continued):
Sharing a sentence is not in itself a finding about the gene and the disease.
hepatitis C (1 paper, 2012). "In contrast to hepatitis C, there is new evidence that highlights an anti-viral role for miR-122 in hepatitis B. In a recent study, cyclin G1 was found to be a direct target of miR-122." (PMID 22783341, 2012).
injury (1 paper, 2018). Damage inflicted on the body as the direct or indirect result of an external force, with or without disruption of structural continuity. "Generally, the low expression level of miR-122 and high expression of Cyclin G1 and CAT-1 at both mRNA and protein levels during INH-induced liver injury suggested that miR-122 could upregulate translation." (PMID 29554950, 2018).
Kashin-Beck disease (1 paper, 2022). Disabling osteochondrodysplasia with osteosclerosis, cone-shaped metaphysis, and shortening of the diaphysis. "The purpose of this study was clarify the relationship between the differential expression of cyclins CCNB1 and CCNG1 and chondrocyte damage in Kashin-Beck disease." (PMID 36588792, 2022). "Finally, the protein expression levels of CCNB1 and CCNG1 were verified in knee cartilage tissue of Kashin-Beck disease patients and normal controls by immunohistochemical staining." (PMID 36588792, 2022). "The differential expression of cyclins CCNB1 and CCNG1 may be related to articular cartilage damage in Kashin-Beck disease." (PMID 36588792, 2022).
liver fibrosis (1 paper, 2025). "Inhibits EMT and liver fibrosis by targeting Cyclin G1 and ADAM17 and maintains the epithelial phenotype." (PMID 40895189, 2025).
lymph node metastasis (1 paper, 2020). "MiR-122-5p was negatively correlated with TNM stage, tumor size, lymph node metastasis and CCNG1." (PMID 32256207, 2020).
lymphoma (1 paper, 2008). A malignant (clonal) proliferation of B- lymphocytes or T- lymphocytes which involves the lymph nodes, bone marrow and/or extranodal sites. "Genes whose expression was “high” in more than 95% of human lymphomas, whose gene names include: BZW2, H2AFY, SFRS3, NAP1L1, NOLA2, UBE2D2 and CCNG1 (p = 4.07×10−5)." (PMID 18535662, 2008).
meningioma (1 paper, 2016). A generally slow growing tumor attached to the dura mater.
nasopharyngeal carcinoma (1 paper, 2017). A carcinoma arising from the nasopharyngeal epithelium. "E2F3 and CCNG1 was identified as targets of miR-203 in nasopharyngeal carcinoma (NPC), while latent membrane protein 1 (LMP1) was responsible for downregulation of miR-203." (PMID 28947999, 2017).
selenium deficiency (1 paper, 2022). A nutritional deficiency disease resulting from inadequate selenium levels in the body, which can lead to impaired function of selenoproteins essential for antioxidant defense and thyroid hormone metabolism. "This evidence combined with T-2 toxin resulting in decreased expression of CCNG1 mRNA suggests that selenium deficiency and T-2 toxin exposure could cause and accelerate chondrocyte apoptosis and necrosis in KBD cartilage partly through regulating CCNB1 and CCNG1." (PMID 36588792, 2022).
cancer (47 papers, 2008 to 2025). A tumor composed of atypical neoplastic, often pleomorphic cells that invade other tissues. "The vector then enters the target cell and delivers its cytocidal CCNG1 inhibitor gene (payload) into the nucleus of rapidly dividing cancer cells, TAFs and neoangiogenic cells, causing cell death via apoptosis-mediated pathways." (PMID 39086973, 2022). "Of these, the only subcluster that might have had any evident impact on cancer outcome was subcluster PN8, which upregulated genes such as Ccng1 that encodes cyclin G1, enabling cancer cells to overcome radiation-induced cell cycle arrest." (PMID 37345658, 2023). "Therefore, based on the positive correlation between FXR and miR-23b-3p, the anti-cancer effects of FXR on OS cell development were associated with the regulation of miR-23b-3p/CCNG1 pathway." (PMID 31779647, 2019). "The involvement of miR-23b–mediated CCNG1 downregulation in inhibiting EOC aggressiveness may yield further insight into the molecular mechanisms underlying cancer aggressiveness." (PMID 26872615, 2016). "The cyclin gene CCNG1 has been reported downregulated and related to a worse overall survival in several cancers." (PMID 39984959, 2025). "The function of miR-122 and its associated mRNAs such as TRIM29, Bcl-W, CCNG1, CDC25A, XIAP, and ALDOA are reportedly downregulated during cancer cell progression." (PMID 36499586, 2022). "Human cyclin G1 (encoded by gene CCNG1) plays important roles during the DNA damage response and its dysfunctions lead to cancers." (PMID 34058988, 2021). "MiR-122 mediated by adenoviral vector was induction of apoptosis and cell cycle arrest of cancer cells by inhibiting Bcl-W and CCNG1 expression." (PMID 33570690, 2021). "CCNG1 dysregulation is described in different kinds of cancer, suggesting its necessary role in tumor development." (PMID 33245102, 2020). "The oncogenic behaviour of CCNG1 has been well documented, and its overexpression has been detected in several types of cancers, yet a cell growth‐inhibitory function of CCNG1 has also been suggested." (PMID 32133790, 2020). "Currently, the potential of companion diagnostics of CCNG1 pathway in the staging, prognosis, and treatment of cancers is widely recognized." (PMID 31779647, 2019). "On the other hand, several reports indicate a cellular growth promoting activity for cyclin G1, since overexpressed cyclin G1 increases cell growth of cancer cells and its silencing reduces cell proliferation." (PMID 27528885, 2016). "Another study showed that abundance of cyclin G1 increased radiosensitivity of cancer cells through activation of cyclin B1, enhanced radiosensitivity was correlated with increased cyclin B1." (PMID 27602752, 2016). "Among the predicted targets of miR-122, ADAM10, IGF1R, and CCNG1 play key roles in tumorigenesis and drug sensitivity in various cancers." (PMID 26514126, 2015). "Overexpression of cyclin G1 enhances the growth of cancer cells, while its silencing suppresses cell proliferation." (PMID 26302777, 2015). "In lungs, miR−23b inhibited cancer cell proliferation by directly targeting CCNG1." (PMID 39858495, 2025). "Thus, the Cyclin G1 oncoprotein represents a singular strategic target and a proximal point of therapeutic intervention in the clinical management of human cancers." (PMID 39086682, 2023). "The authors of the study identified Delta-Rex-G as a potential intervention, noting its impressive results regarding long-term cancer-free survival in clinical trials, and suggesting clinical evaluation of the anti-CCNG1 strategy as a treatment in such cases with very poor prognosis." (PMID 39086682, 2023).
cancer (continued). "According to the prediction results from the miRNA bioinformatics websites, we found that CCNG1, an oncogene in many human cancers, might be a target gene of miR-122-5p." (PMID 32256207, 2020). "On the basis of other investigations, it can be presumed that lncRNA-SBF2-AS1 orchestrates various signaling pathways to positively regulate the progression of cancer since that miRNA-122-5p can target other genes, such as cyclin G1 (CCNG1), and that lncRNA-SBF2-AS1 is known to sponge other miRNAs." (PMID 32756339, 2020). "Moreover, a strong correlation between Notch3 and CCNG1 expression levels supports a role of both Notch3 and CCNG1 in cancer progression." (PMID 30565428, 2019). "In vivo, knockdown expression of CCNG1 inhibited cancer metastasis." (PMID 30565428, 2019). "This upregulation of miR-141-3p and/or miR-200a-3p may have effects on several cancer-related target genes that have been previously associated with these two miRNAs, including E2F3, GLS, CCND2, PTEN, CCNG1, CDC25B, and ZFPM2." (PMID 28288173, 2017). "This processis known to inhibit apoptosis and thus leads to tumors with unrestricted growth.Additionally, the increase of miR-122 in HCC could inhibit cyclin G1 and the cellcycle arrest in the G2/M phase, which could inhibit the proliferation of cancer cells." (PMID 25012758, 2014). "As a proto-oncogene, cyclin G1 is closely related to cancer." (PMID 25012758, 2014). "Thus, CCNG1 may serve as a marker for the sensitivity of cancers to anti-mitotic therapy through regulating the outcome of taxane-induced mitotic arrest." (PMID 26152689, 2015). "CCNG1 and EDG1 both show a dual role in cancer since they can positively or negatively regulate cell growth." (PMID 39984959, 2025). "Bioinformatics algorithms including TargetScan, miRWalk, miRDB, and MicroRNAs in cancer (KEGG) were employed and CCNG1 was obtained." (PMID 33245102, 2020). "CCNG1 could stimulate and propel PP2A catalytic activity toward E3 ubiquitin-protein ligase (Mdm2), which has increased or abnormal expression in numerous cancer types including OS." (PMID 31779647, 2019). "Moreover, a strong correlation was evident between Notch3 and PCNA and between Cyclin G1 and PCNA supporting a role of both Notch3 and Cyclin G1 in cancer progression." (PMID 25431954, 2014). "By comparing the lists of top-ranking cancer-related target genes, we were able to identify seven promising cancer-related genes that may be targets of the hsa_circRNA_100395/miR-141-3p/ miR-200a-3p axis in PTC (in order of descending rank): E2F3, GLS, CCND2, PTEN, CCNG1, CDC25B, and ZFPM2." (PMID 28288173, 2017).
tumor (43 papers, 2007 to 2025). "CCNG1 is a target for miR-23b-3p, indicating that the tumor-suppressive effects of FXR may be highly associated with miR-23b-3p/CCNG1 pathway." (PMID 31779647, 2019). "Hypothesis: A brief administration of DeltaRex-G, a tumor targeted retroviral vector encoding a cytocidal mutated cyclin G1 gene, would inhibit only the dividing T cells thus reducing cytokine release by hyperactive CAR-T cells while retaining their antitumor efficacy." (PMID 39359418, 2024). "Following an inquiry into the molecular mechanisms orchestrating cytokine release syndrome, we hypothesize that DeltaRex-G, a tumor targeted retrovector encoding a cytocidal CCNG1 inhibitor gene, may be a viable treatment option for corticosteroid-resistant cytokine release syndrome." (PMID 39359418, 2024). "miR-122 overexpression in HepG2 cells decreases cyclin G1 levels and radiosensitizes tumor grafts in mice." (PMID 39590305, 2024). "Previous studies have shown that miR-122 targets genes such as cyclin G1 and laminin B2, both of which are involved in tumor progression." (PMID 39590305, 2024). "Here, we report on the results of a Phase I/II study using DeltaRex-G, a tumor-targeted retrovector bearing a CCNG1 inhibitor gene for chemotherapy resistant advanced carcinoma of breast." (PMID 39086675, 2023). "miRNA-122 exerts its tumor suppressive effect by inhibiting cyclin G1, inhibiting the insulin-like growth factor 1 receptor pathway, inhibiting the expression of toll-like receptor 4 in tumor cells, etc.." (PMID 37546394, 2023). "Some miRNAs has been reported to interact with CCNG1 to affect tumor progression and chemoresistance." (PMID 33245102, 2020). "In vitro, CCNG1 promoted both tumor cell motility by inducing epithelial‐mesenchymal transition (EMT) and resistance to cisplatin (CDDP)." (PMID 30565428, 2019). "Our subsequent in vivo tumor xenograft studies showed that miR-23b inhibited tumor growth and decreased CCNG1 expression." (PMID 26872615, 2016). "Immunofluorescence staining (IF) indicated decreased CCNG1 expression in the tumor xenografts of the miR-23b–treated nude mice compared with that in the mock-treated nude mice." (PMID 26872615, 2016). "The role of cyclin G1 is controversial, since it was shown to act as oncogene or tumour suppresor gene, depending on cellular context and different experimental settings." (PMID 22235305, 2012). "Phase 2 randomized studies with an expanded sample size are planned for 2025 to further evaluate the efficacy and safety of DNG64+ and to correlate CCNG1 expression level and circulating tumor DNA (ctDNA) level with treatment outcome parameters in response to DNG64+ gene therapy." (PMID 40227707, 2025). "Furthermore, the upregulation of tumour suppressor miR-122 by activated FXR suppressed the insulin-like growth factor-1 receptor (IGF-1R) and cyclin G1 resulting in decreased cell proliferation in cancer cells and tumour growth in a mouse model." (PMID 35006466, 2021). "Previous studies have demonstrated the promoting effects of CCNG1 on cell growth and that the inhibition of CCNG1 could effectively suppress the growth of human tumor xenografts in a nude mouse model." (PMID 31779647, 2019).
tumor (continued). "Furthermore, miR-23b inhibited tumor growth and suppressed CCNG1 expression in vitro." (PMID 26872615, 2016). "Among them, we selected seven genes associated to cell proliferation and apoptosis that resulted downregulated in tumor samples: BTG1, CCNG1, DMD, EDG1, SEMA3G, SYNPO2, TIMP2." (PMID 39984959, 2025). "An example of utilizing miRNA targets is the attempt of enhancing the tumor-suppressing effect of miR-122, which targets ADAM10, IGF1R, as well as cyclin G1 and ADAM17." (PMID 37108330, 2023). "Our data are therefore consistent with a role of miR‐27a as tumour suppressor and that its downregulation leads to an upregulation of the pro‐oncogenic CBLB and CCNG1." (PMID 32133790, 2020). "The expression levels of CCNO were higher in tumour cell lines than in the normal one, while CCNY and CCNG1 exhibited higher expression in HT-29 cells." (PMID 30087414, 2018). "Understanding the contribution of desregulated miRNAs to HCC requires the identification of gene targets and in this sense, cyclin G1 and the PTEN tumor suppressor gene have been found to be regulated by miR-122a and miR-21, respectively." (PMID 23226427, 2012). "In addition, protein expression analysis of BTG1, CCNG1, EDG1, and TIMP2 in MM tissues in mouse tumor masses treated with LNPs-anti-miR-503 confirmed the q-PCR results and the opposite expression of miR-503 and of its target genes also in vivo." (PMID 39984959, 2025). "Furthermore, CCNG1, which is up-regulated in various tumor tissues, has not yet been identified as a GC diagnosis biomarker." (PMID 40150719, 2025). "Administration of a dominant negative form of cyclin G1, also known as Rexin-G, using retroviral vector injection into the hepatic artery, has also been tested in the liver metastasis of colorectal tumors (NCT00035919) and has shown significant anti-tumor activity in pancreatic cancer." (PMID 31769427, 2019).
infection (6 papers, 2011 to 2019). The state of being infected such as from the introduction of a foreign agent such as serum, vaccine, antigenic substance or organism. "Next, the expression of p21 and cyclin G1 under the disruption of N protein during SVCV infection was also confirmed." (PMID 30925159, 2019). "E2 and progesterone treatment (either alone or combined) enhanced the expression of cyclin G1, whereas infection of MCF-7 cells with shCyclin G1 significantly decreased the mRNA level of cyclin G1." (PMID 29513878, 2018). "Nevertheless, the infection was also able to repress cell cycle related genes, such as cyclin G1 (CCNG1), regulator of cell cycle (RGCC), and synaptonemal complex protein 3 (SYCP3)." (PMID 27197554, 2016). "Genes involved in cell cycle like Cyclin G1, G2 were down-regulated at all the time points post infection." (PMID 21439068, 2011). "The protein level of cyclin G1 was also consistently decreased upon infection with shCyclin G1." (PMID 29513878, 2018). "QRT-PCR analysis revealed that at early stage of infection (day 1 p.i.), mRNA levels of cell cycle genes such as CDC2, CDC25A, Cyclin E, CDK5, CDK8 and Cyclin G1 were significantly (P<0.05) upregulated in A. phagocytophilum-infected cells in comparison to uninfected controls." (PMID 28797056, 2017).
CCNG1 also shares sentences with these, for which no sentence is quoted: metastatic carcinoma (3 papers); prostate carcinoma (3); acute myeloid leukemia (2); colorectal cancer (2); hepatoblastoma (2); metastatic disease (2); alopecia (1); asthma (1); B-cell lymphoma (1); benign ovarian tumors (1); benign tumors (1); bladder cancer (1); bone cancer (1); bronchopulmonary dysplasia (1); Burkitt lymphoma (1); cardiomyopathy (1); cardiovascular diseases (1); cervical carcinoma (1); colon cancer (1); COVID-19 (1); dementia (1); dengue (1); Diabetic Nephropathy (1); dilated cardiomyopathy (1); esophageal squamous cell carcinoma (1); hepatitis B (1); leiomyoma (1); lung adenocarcinoma (1); malignant peripheral nerve sheath tumor (1); mantle cell lymphoma (1).
A further 10 diseases each share a sentence with CCNG1 in 1 paper.